HLA-G (major histocompatibility complex, class I, G)
Diseases named in the same sentence as HLA-G in open-access papers (continued):
Sharing a sentence is not in itself a finding about the gene and the disease.
prostatic adenocarcinoma (2 papers, 2018 to 2025). "Glandular epithelia and/or secretions in normal prostate (n=5) and prostatic adenocarcinoma (n=4) were found to express HLA-G." (PMID 41181133, 2025).
rectal adenocarcinoma (2 papers, 2021 to 2023). "HLA-G expression was significantly associated with the pathological stage of breast invasive carcinoma (BRCA) (P=0.044), KIRP (P=0.031), rectal adenocarcinoma (READ) (P=0.008), and THCA (P=3E-04)." (PMID 34276642, 2021). "Likewise, the results indicated that the expression level of HLA-G was not related to OS in rectal adenocarcinoma (READ) patients." (PMID 37875821, 2023).
skin cancer (2 papers, 2021 to 2022). "As immunotherapies are increasingly used to direct the body’s immune system against tumor, overexpression of PD-L1 and HLA-G by keratinocyte precursors should be considered in understanding the function of skin tumor initiator cells." (PMID 35222373, 2022).
Stroke (2 papers, 2012 to 2023). Sudden impairment of blood flow to a part of the brain due to occlusion or rupture of an artery to the brain. "Brain sections stained for HLA-G antibody revealed that hAECs injected i.v. at 1.5 h post-stroke were present in the ischemic hemisphere within 6 h (n = 9 mice)." (PMID 37397458, 2023). "Serum HLA-G levels were similar in patients with and without obstetric events, arterial thrombosis, venous events, and stroke (P > 0.05) (Mann-Whitney test)." (PMID 22654952, 2012).
tuberculosis (2 papers, 2016 to 2024). A chronic, recurrent infection caused by the bacterium Mycobacterium tuberculosis. "The immune inhibitory receptor leukocyte immunoglobulin like receptor B1 (LILRB1), which is upregulated and activated by human leukocyte antigen-G (HLA-G), drives natural killer (NK) cell exhaustion in tuberculosis (TB) patients, thus serving as a promising target for TB immunotherapy." (PMID 39030302, 2024).
ZIKV infection (2 papers, 2022 to 2025). "ZIKV infection causes endoplasmic reticulum stress in trophoblasts, leading to down-regulation of HLA-C and HLA-G." (PMID 40358173, 2025).
acral lentiginous melanoma (1 paper, 2025). A form of melanoma occurring most often on the plantar, palmar, subungual, and periungual skin. "Although only two samples from acral lentiginous melanoma patients were included in our cohort, this subtype showed the highest LEVs-HLA-G+ counts." (PMID 41268555, 2025).
alveolar soft part sarcoma (1 paper, 2023). An alveolar soft part sarcoma occurring in adults. "Furthermore, HLA-G transcripts were rarely detected from patient tumor RNA-Seq using HLA-HD or HLAProfiler, with the exception of all four alveolar soft part sarcoma tumors (data not shown)." (PMID 38318504, 2023).
aneuploidy (1 paper, 2018). Chromosomal disorder consisting of the presence a chromosomal abnormality in which there is an addition or loss of chromosomes within a set. "Linear regression between the HLA-G +3142/+3187 diplotypes and presence of aneuploidy in cervical cells from HIV-infected women." (PMID 30278059, 2018).
astrocytoma (1 paper, 2018). "In infected cells CMV also reduces the expression of surface HLA-G and increases the levels of soluble HLA-G, as evidenced by experiments on U-373 MG astrocytoma cells." (PMID 29467963, 2018).
atherosclerosis (1 paper, 2014). A disease characterized by the build-up of fatty material and calcium deposition in the arterial wall resulting in partial or complete occlusion of the arterial lumen. "Furthermore, HLA-G can be expressed by endothelial cells, which are a key in the regulation of the atherosclerosis process." (PMID 24689061, 2014).
Azoospermia (1 paper, 2014). Absence of any measurable level of sperm,whereby spermatozoa cannot be observed even after centrifugation of the semen pellet. "We further compared the HLA-G mRNA expression in testicular tissues from azoospermia patients with Johnsen score of 8–9 and those with normal semen parameters." (PMID 24667226, 2014). "Except for testicular tissues from azoospermia patients, two testicular tissues retrieved from normospermic patients due to difficulty in semen collection on the day of oocyte retrieval were also examined for HLA-G mRNA expression." (PMID 24667226, 2014).
B-cell lymphoma (1 paper, 2024). "In the Raji B-cell lymphoma cell line, HLA-G inhibited proliferation through induction of G0/G1 cell-cycle arrest and inhibition of the PKC and AKT/mTOR pathways." (PMID 39696628, 2024). "The LILRB1 ligand HLA-G inhibits the proliferation of B-cell lymphoma, MM, and pre-B-cell leukemia cell lines." (PMID 39696628, 2024).
benign ovarian tumor (1 paper, 2008). "Methylation within the regulatory region of the HLA-G gene also was examined in eighteen malignant and benign ovarian tumor samples and in ovarian surface epithelial cells (OSE) isolated from four patients with normal ovaries." (PMID 18498645, 2008). "To test this hypothesis in tissues, we analyzed methylation of the HLA-G 5' regulatory region in 4 OSE samples and 18 malignant and benign ovarian tumor samples." (PMID 18498645, 2008).
brain cancer (1 paper, 2009). A primary or metastatic malignant neoplasm affecting the brain. "In brain cancer, low expression of classical HLA class I genes (HLA-A, -B, and –C) coupled with up-regulation of nonclassical genes (e.g., HLA-E and HLA-G) likely contributes to immune escape by tumor cells with various somatic mutations." (PMID 19774073, 2009).
brain glioma (1 paper, 2022). A malignant glioma that involves the brain. "In a group of 59 patients with brain gliomas and 159 controls, the presence of 14 nt insert (14 ins) in the 3′UTR region of HLA-G by PCR was analyzed." (PMID 35626255, 2022).
calcinosis (1 paper, 2021). Deposition of calcium in the tissues. "Additionally, the researchers’ correlation of clinical features with the presence of HLA-G showed that HLA-G expression was associated with a lower incidence of skin lesions (calcinosis and telangiectasia), changes in blood vessels (ischemic skin ulcers) and changes in internal organs." (PMID 34948145, 2021).
choroidal neovascularization (1 paper, 2022). An eye disorder described by the growth of new blood vessels that originate from the choroid through a break in the Bruch membrane into the sub–retinal pigment epithelium (sub-RPE) or subretinal space. "Furthermore, due to the anti-vascular function of HLA-G, AAV-HLA-G may be an effective therapy for posterior ocular diseases, such as neovascular age-related macular degeneration, diabetic retinopathy, and choroidal neovascularization." (PMID 35408825, 2022).
chronic hepatitis C (1 paper, 2024). "Plasma-soluble human leukocyte antigen-G (HLA-G) levels are elevated in CHB and chronic hepatitis C patients compared to healthy controls." (PMID 38398102, 2024).
chronic kidney disease (1 paper, 2019). Impairment of the renal function secondary to chronic kidney damage persisting for three or more months. "Regarding the association tests performed for chronic kidney disease patients, the HLA-G*01:01/UTR-4 was found to be a protective factor for the development of chronic kidney disease (FET analysis)." (PMID 30794652, 2019).
colitis (1 paper, 2019). Inflammation of the colon. "Further studies are required to determine whether the same signaling pathway is involved in both exosomal HLA-G and free HLA-G-induced regulation of colitis." (PMID 31316512, 2019).
coronary stenosis (1 paper, 2020). Narrowing of the coronary artery lumen diameter. "Epigenetics phenomena induce hypomethylation of specific regions into 5'UTR-CpG island of HLA-G gene in CHD patients with obstructive non critical stenosis vs coronary stenosis individuals." (PMID 32790754, 2020).
cyst (1 paper, 2021). A sac-like closed membranous structure that may be empty or contain fluid or amorphous material. "We also detected expression of the extravillous trophoblast marker HLA-G in cyst outgrowths." (PMID 33831366, 2021).
dengue (1 paper, 2025). "Studies have reported an upregulation of HLA‐G antigens upon DENV infections suggesting a role of the ICPs in the pathogenesis of dengue." (PMID 40910405, 2025). "HLA‐G is known for its tolerogenic role suppressing the activity of effector cells, in particular NK cells and CD8+ cytotoxic T lymphocytes and thus might be potentially involved in the pathogenesis of dengue." (PMID 40910405, 2025).
dental caries (1 paper, 2020). The decay of a tooth, in which it becomes softened, discolored, and/or porous. "In particular, HLA-G upregulation has been reported in studies of bacterial infections; however, there is no study about the role of salivary sHLA-G in dental caries." (PMID 32676113, 2020).
dyslipidemia (1 paper, 2022). "Low expression of HLA-G in patients with HLA-G 14bp was associated with dyslipidemia." (PMID 35769475, 2022).
erythroleukemia (1 paper, 2022). Acute erythroid leukemia characterised by the presence of at least 50% erythroid precursors and at least 20% myeloblasts in the bone marrow. "To confirm the immune-inhibitory potential of HLA-G, we constructed HLA-G-overexpressing K562 cells; this human erythroleukemia cell line lacks HLA-I expression and is thus highly vulnerable to NK cells." (PMID 36032723, 2022).
fibrosarcoma (1 paper, 2012). A malignant mesenchymal fibroblastic neoplasm affecting the soft tissue and bone. "HLA-G was repressed in HT1080 cells derived from a fibrosarcoma, but was expressed in JEG3 cells from a placental source." (PMID 23002136, 2012).
follicular thyroid carcinoma (1 paper, 2021). "Despite that only a particular subset of HLA-G isoforms was stained for, all patients with papillary as well as follicular thyroid carcinoma were deemed HLA-G positive." (PMID 34361031, 2021).
glomerulonephritis (1 paper, 2025). A renal disorder characterized by damage in the glomeruli. "In recipients, HLA-G 3′UTR-1 homozygosity was associated with underlying primary diseases such as glomerulonephritis." (PMID 41562090, 2025). "Interestingly, we found that HLA-G 3′UTR-1 homozygosity was associated with underlying primary diseases such as glomerulonephritis, a group of primary diseases for which genetic predisposition has been implicated." (PMID 41562090, 2025).
histiocytic lymphoma (1 paper, 2019). "Among liquid tumor cell lines, the data revealed that all cell lines such as histiocytic lymphoma (monocyte) U937 cells could acquire HLA‐G protein from autologous HLA‐G‐transfected U937 (U937‐HLA‐G) and allogeneic HLA‐G‐transfected LCL‐721.221 cells (LCL‐HLA‐G1)." (PMID 31489189, 2019).
hyperuricemia (1 paper, 2021). An abnormally high level of uric acid. "Differentially methylated regions (e.g. HLA-G, IFITM3, PRKAB2) were found in people with hyperuricemia compared to normouricemia in genes relevant for inflammatory cytokine signaling." (PMID 34321071, 2021).
idiopathic pulmonary fibrosis (1 paper, 2021). Idiopathic pulmonary fibrosis (IPF) is a nonneoplastic pulmonary disease that is characterized by the formation of scar tissue within the lungs in the absence of any known cause. "The HLA-G+ cells did not match the CD117+ cells in lung fibrosis." (PMID 34830373, 2021).
Immunodeficiency (1 paper, 2024). Failure of the immune system to protect the body adequately from infection, due to the absence or insufficiency of some component process or substance. "Also, as shown in the experiment using the immunodeficiency mouse model, we found that HLA-G expression could be modulated by hypoxia and by IL-6 production." (PMID 38877399, 2024).
intracranial meningioma (1 paper, 2020). A meningioma that arises within the cranial cavity.
invasive carcinoma (1 paper, 2019). A carcinoma that is not confined to the epithelium, and has spread to the surrounding stroma. "HLA-G expression was increased in benign and premalignant lesions, and gradually decreased in invasive carcinomas and in respective draining cervical lymph nodes." (PMID 31739287, 2019).
Iron deficiency (1 paper, 2014). "Iron deficiency prevented NGAL-mediated effects, such that HLA-G expression was unaltered." (PMID 24586826, 2014).
kidney (1 paper, 2014). "The high levels of sHLA-G dimers were associated also with increased expression of the membrane-bound form of HLA-G on monocytes from patients that have no rejection episode of kidney transplant." (PMID 24741575, 2014).
leprosy (1 paper, 2013). Leprosy is a chronic infectious disease affecting primarily the skin and peripheral nervous system. "3′ UTR polymorphisms (+3187A-A and A-G genotypes) associated with low HLA-G expression were also associated with susceptibility to the development of PB leprosy." (PMID 24498610, 2013). "In conclusion, we showed that gene polymorphic sites associated with the modulation of the immunoregulatory HLA-G molecule are associated with polar forms of leprosy." (PMID 24498610, 2013). "The HLA-G + 3187A polymorphic site, which is related to unstable mRNA production, was associated with the development of polar forms of leprosy and reactive leprosy reaction." (PMID 24498610, 2013). "Further studies evaluating HLA-G soluble levels should clarify the immunomodulatory role of HLA-G in the immune response in leprosy." (PMID 24498610, 2013). "Taken together, these observations suggest a possible role of HLA-G in the model of leprosy pathogenesis." (PMID 24498610, 2013).
lip squamous cell carcinoma (1 paper, 2019). "The impact of combined expression of IL-10 and HLA-G has been evaluated in lip squamous cell carcinoma (LSCC), where high levels of HLA-G and IL-10 protein expression could be observed only in carcinoma lesions but not in normal tissues." (PMID 31013867, 2019).
liver cirrhosis (1 paper, 2021). "Thus, the expression of HLA-G is not restricted to the viral etiology of liver cirrhosis." (PMID 34830373, 2021).
meningioma (1 paper, 2020). A generally slow growing tumor attached to the dura mater. "We risk the hypothesis that the high HLA-G positivity in our samples could be contributing to the high recurrence/regrowth rates (14.6%) in grade I meningiomas by inhibiting immune surveillance." (PMID 32903787, 2020). "To date, no other studies evaluating the tissue expression of HLA-G in meningiomas have been published." (PMID 32903787, 2020). "In our research, all the meningioma samples presented 100% HLA-G positivity, thus it was not possible to perform statistical analyses with the other variables." (PMID 32903787, 2020).
metastasis (1 paper, 2023). The spread or migration of cancer cells from one part of the body (where they first appeared) to another. "Nevertheless, the expression of HLA-G is not related to age, sex, tumor type, tumor differentiation, TNM stage, or distant metastasis but lymph node metastasis." (PMID 37875821, 2023).
mucoepidermoid carcinoma (1 paper, 2024). A carcinoma morphologically characterized the presence of cuboidal mucous cells, goblet-like mucous cells, squamoid cells, cystic changes, and a fibrotic stromal formation. "The enhanced HLA-G expression in lip carcinogenesis, oral precancerous lesions and intraoral mucoepidermoid carcinoma has been also identified." (PMID 38391781, 2024).
nasal polyps (1 paper, 2014). "Since HPV infection modifies HLA-G expression, we analyzed the different fraction of cells extracted from nasal polyps for HLA-G expression." (PMID 24741599, 2014). "In conclusion, this is the first study elucidating the possible involvement of IL-10/HLA-G feedback loop in maintaining HPV infection in nasal polyps from SNP-WoAD patients." (PMID 24741599, 2014). "Since previous studies reported an involvement of HLA-G molecules in HPV-associated tumours, we determined the presence of HPV infection and HPV types in the nasal polyps of patients affected by SNP and the possible effect on HLA-G expression." (PMID 24741599, 2014).
Nephropathy (1 paper, 2025). A nonspecific term referring to disease or damage of the kidneys. "In our previous study the HLA-G 3 ́UTR-4 in both donor and recipient has been linked to an increased risk of BK polyomavirus (BKPyV) nephropathy and CMV replication following transplantation." (PMID 41562090, 2025).
neuropathy (1 paper, 2017). A disorder affecting the nervous system that manifests with pain, tingling, numbness, and/or muscle weakness. "This study demonstrated that the HLA-G 3′UTR SNPs, rs1610696, rs371194629, and the UTR-2 haplotype, should be considered markers with potential clinical value in predicting G3-4 CT-toxicities, particularly toxicities related to neuropathy." (PMID 28653974, 2017).
neutropenia (1 paper, 2017). A decrease in the number of neutrophils found in the blood. "HLA-G 3′UTR-2, which contains rs1610696-G/G and rs371194629-Ins/Ins polymorphisms, was associated with increased risk of G3-4 neutropenia (OR = 3.92, p = 0.017) and neurotoxicity (OR = 11.29, p = 0.009)." (PMID 28653974, 2017).
ovarian adenocarcinoma (1 paper, 2017). An adenocarcinoma that arises from the ovary. "All the 19 CpG sites were methylated in the BG-1 ovarian adenocarcinoma cells (HLA-G−) and a region of 79 bp (−211 to −290) containing −242 HRE remained methylated after 5 days with 5-aza-dC 50 μM treatment." (PMID 28781970, 2017).
placental disorders (1 paper, 2023). "HLA-G is uniquely expressed in the extravillous trophoblast (EVT) and has been linked to placental disorders." (PMID 37006248, 2023).
pulmonary tuberculosis (1 paper, 2025). A bacterial infection that affects the lungs and is caused by Mycobacterium tuberculosis. "The expression of HLA-G showed significant differences between pulmonary tuberculosis (PTB) and endometrial tuberculosis (ETB) lesion and peri-lesion tissues." (PMID 40375897, 2025). "Immunohistochemical analysis further revealed that the expression levels of HLA-G and IP-10 were significantly higher in the lesion areas of the endometrial tuberculosis (ETB) group compared to pulmonary tuberculosis (PTB) patients." (PMID 40375897, 2025). "In conclusion, endometrial tuberculosis (ETB) exhibit distinct immunological features compared to pulmonary tuberculosis (PTB), particularly in the expression of macrophages CD68, HLA-G, and IL-1Ra." (PMID 40375897, 2025). "The pathological characteristics of endometrial tuberculosis (ETB) and pulmonary tuberculosis (PTB) do not show significant differences; however, notable distinctions are observed in the expression of immune cells and inflammatory factors, particularly macrophages, HLA-G, IP-10, and IL-1Ra." (PMID 40375897, 2025).
rectal tumors (1 paper, 2014). "In conclusion, rectal tumors showing loss of HLA class I expression, Foxp3+ infiltration below median and weak HLA-G expression were related to a worse OS and DFS." (PMID 24997850, 2014).
renal fibrosis (1 paper, 2021). A final common manifestation of a wide variety of chronic kidney diseases characterized by glomerulosclerosis and tubulointerstitial fibrosis. "In the study of a series of 10 cases of renal fibrosis by immunochemistry, we found 133 ± 102 HLA-G+ cells/mm2 and 426 ± 207 CD117+ cells/mm2." (PMID 34830373, 2021). "We characterized HLA-G expression in mast cells and immune cells on paraffin blocks of cohorts of 41 patients with alcohol-induced cirrhosis, 10 with IPF, and 10 with renal fibrosis." (PMID 34830373, 2021). "HLA-G+ and CD117+ cells were counted for 10 cases of renal fibrosis using HALO software with the appropriate algorithm, following immunohistochemistry." (PMID 34830373, 2021).